CCT6A (chaperonin containing TCP1 subunit 6A)
Description:
Component of the chaperonin-containing T-complex (TRiC), a molecular chaperone complex that assists the folding of actin, tubulin and other proteins upon ATP hydrolysis. The TRiC complex mediates the folding of WRAP53/TCAB1, thereby regulating telomere maintenance.
Synonyms: TCP-1-zeta; CCT6; CCTZ; TTCP20; TCPZ; HTR3; TCP20; CCT-zeta; CCT-zeta-1; MoDP-2
Tractability: Small molecule: a structure with a bound ligand is known. PROTAC: UniProt records ubiquitination sites on it; ubiquitination databases record sites on it; its protein half-life has been measured.
Target class: Enzyme; Hydrolase
Gene: Protein-coding gene on chromosome 7 (56,051,685 to 56,063,991, forward strand). Ensembl gene ENSG00000146731.
Subcellular location: Cytoplasm
Subcellular location (Human Protein Atlas): Cytosol
Pathways (Reactome):
Metabolism of proteins: Association of TriC/CCT with target proteins during biosynthesis; Cooperation of PDCL (PhLP1) and TRiC/CCT in G-protein beta folding; Folding of actin by CCT/TriC; Formation of tubulin folding intermediates by CCT/TriC; Prefoldin mediated transfer of substrate to CCT/TriC
Signal Transduction: RHOBTB2 GTPase cycle
Gene Ontology:
Molecular function: protein binding; protein folding chaperone; RNA binding; WD40-repeat domain binding; ATP binding; ATP hydrolysis activity; ATP-dependent protein folding chaperone
Biological process: positive regulation of establishment of protein localization to telomere; positive regulation of protein localization to Cajal body; positive regulation of telomerase RNA localization to Cajal body; positive regulation of telomere maintenance via telomerase; protein folding; protein stabilization
Cellular component: chaperonin-containing T-complex; extracellular exosome; microtubule; cytoplasm; cytosol
Genetic constraint (gnomAD): Loss-of-function variants: 2 observed, 26.91 expected, observed/expected ratio (o/e) 0.0743, 90% interval 0.029 to 0.23. The upper end of that interval is the gene's LOEUF score, 0.23, which puts it in group 1 of 6, group 1 being the genes least tolerant of losing a copy. Missense variants: 315 observed, 392.28 expected, observed/expected ratio (o/e) 0.8, 90% interval 0.73 to 0.88. Synonymous variants: 161 observed, 145.62 expected, observed/expected ratio (o/e) 1.11, 90% interval 0.97 to 1.26.
Homologues: Orthologues: chimpanzee CCT6A (100% identical), macaque CCT6A (99% identical), rat Cct6a (97% identical), guinea pig CCT6A (97% identical), mouse Cct6a (97% identical). Paralogues in human: CCT6B (86% identical), CCT5 (30% identical), CCT7 (28% identical), CCT4 (27% identical), TCP1 (27% identical), CCT3 (27% identical), CCT8 (26% identical), CCT2 (26% identical), PIKFYVE (26% identical), CCT8L2 (22% identical), HSPD1 (22% identical), MKKS (18% identical), and 1 more.
Diseases named in the same sentence as CCT6A in open-access papers:
CCT6A is named in the same sentence as 53 diseases in open-access papers, as found by Europe PMC text mining. Sharing a sentence is not in itself a finding about the gene and the disease. The quoted sentences say what the papers report.
breast cancer (14 papers, 2019 to 2025). A primary or metastatic malignant neoplasm involving the breast. "One bioinformatic analysis reported that overexpression of CCT6A in tumor tissue was associated with poor breast cancer prognosis." (PMID 36998462, 2023). "CCT6A expression was shown to be increased in 10 human tumor cell lines and associated with poor survival in lung cancer, breast cancer, and glioblastoma." (PMID 33897772, 2021). "Similar to CCT3, overexpression of CCT6A has been found in many malignancies, including liver cancers as well as breast cancer and lung cancer, and is associated with clinical prognosis and TNM stage." (PMID 34676169, 2021). "For example, CCT6A is upregulated in breast cancer tissue, HCC tissue, and colorectal cancer tissue compared with the matched noncancerous tissue." (PMID 32631353, 2020). "According to our studies, three subunits of CCT complex – CCT1, CCT2 and CCT6A strongly correlated with survival of breast cancer patients." (PMID 31101846, 2019). "Herein, using The Cancer Genome Atlas and KM plotter database, we showed strong association between expression of at least six HSP-encoding genes (namely: HSPA2, DNAJC20, HSP90AA1, CCT1, CCT2 and CCT6A) and survival of breast cancer patients." (PMID 31101846, 2019). "Collectively, these results suggest that high expression of HSPA2 and DNAJC20 is associated with low-risk breast cancer, whereas high expression of HSP90AA1, CCT1, CCT2 and CCT6A correlates with high-risk breast cancer." (PMID 31101846, 2019). "In the progression of breast cancer and hepatocellular carcinoma, CCT6A plays a vital role." (PMID 39556022, 2024). "Similarly, pathway analysis positively correlated CCT6A with G2-M phase cyclins B and A in breast cancer." (PMID 35602608, 2022). "Besides, several clinical practices illuminate that CCT6A correlates with deteriorated tumor features and unsatisfactory prognosis in patients with several cancers (including breast cancer, HCC, and colorectal cancer)." (PMID 32631353, 2020). "Interestingly, patients overexpressing two identified HSPs – HSPA2 and DNAJC20 exhibited longer survival, whereas overexpression of other four HSPs – HSP90AA1, CCT1, CCT2, CCT6A resulted in unfavorable prognosis for breast cancer patients." (PMID 31101846, 2019). "Furthermore, CCT6A high expression correlates with elevated clinical stage, larger tumor size, nodal statu,s and Scarff–Bloom–Richardson grade in breast cancer patients; and its high expression correlates with larger tumor size as well as severer tumor invasion in colorectal cancer patients." (PMID 32631353, 2020). "Besides, CCT6A expression is negatively correlated with distant metastasis-free survival, DFS, post-progression survival, and OS in breast cancer patients." (PMID 32631353, 2020). "CCT itself could activate genes that drive cell cycling, since overexpression of CCT2 in luminal A breast cancer cells increased the gene expression of MYC and CCND1 that statistically correlated with CCT2, while depletion of CCT6A in an HCC cell line decreased levels of cyclin D." (PMID 35602608, 2022).
glioblastoma (10 papers, 2020 to 2025). The most malignant astrocytic tumor (WHO grade IV). "Among these, CCT2, CCT3, CCT5, CCT6A, CCT7, and TCP1 were increased in the EVs of glioblastoma patients; CCT6A was proposed as a biomarker, as it was associated with decreased survival." (PMID 34631760, 2021). "CCT4 participates in protein CCT6A as a potential prognostic biomarker in glioblastoma." (PMID 33313411, 2020). "Increased expression of CCT2, CCT6A, and CCT7 in EVs from cavitron ultrasonic surgical aspirators (CUSA) samples in glioblastoma patients correlated with poor patient prognosis." (PMID 35749519, 2022). "Moreover, studies with glioblastomas demonstrated CCT6A, CCT1, CCT2, and CCT7 subunits increased in the tumor tissue and tumor-derived extracellular vesicles, particularly CCT6A." (PMID 40374617, 2025).
lung carcinoma (10 papers, 2020 to 2025). "It has been found that high CCT6A expression promotes the invasion and metastasis of various malignancies, including liver and lung cancers." (PMID 40953006, 2025). "Numerous studies have examined the role of CCTs, such as CCT3, CCT5, and CCT6A, in lung cancer, particularly NSCLC." (PMID 39259093, 2024). "For lung cancer, there is only one investigation shows the correlation of CCT6A with worse survival in NSCLC patients (which is only supported by gene expression analysis in TCGA)." (PMID 32631353, 2020). "As for lung cancer, one experiment displays that CCT6A enhances NSCLC cell metastasis." (PMID 32631353, 2020). "For instance, in 2014, a systematic multi-omic analyses on lung cancer have revealed a group of potential multi-omic biomarkers for lung cancer, including EGFR and CCT6A." (PMID 33767734, 2021). "Furthermore, Analysis of CPTAC protein dataset in UALCAN database showed that CCT6A was significantly overexpressed in colon cancer, ovarian cancer, clear cell RCC (renal cell carcinoma), UCEC, lung cancer, and liver cancer." (PMID 39440061, 2024). "Recurrent EGFR fusions included CCT6A-EGFR fusions in two cases of lung cancer (2/13, 15.4%) and intergenic EGFR-SEC61G fusions, occurring at intergenic regions downstream of SEC61G, in three cases of gastric cancers and one case of lung cancer." (PMID 36369474, 2022). "Among them, EGFR-VSTM2A, CCT6A-EGFR, and ERBB2-IKZF3 have not previously been documented in lung cancer." (PMID 34508169, 2021).
colorectal cancer (6 papers, 2020 to 2025). A primary or metastatic malignant neoplasm that affects the colon or rectum. "Furthermore, Li and colleagues highlighted CCT6A as a marker for the pre‐exhausted T‐cell subset in colorectal cancer." (PMID 39556022, 2024). "High CCT6A expression has potential value in the prognosis colorectal cancer liver metastasis." (PMID 34335929, 2021). "CCT6A was knockout by CRISPR-Cas9, and overexpressed by transfecting plasmids in colorectal cancer (CRC) cells." (PMID 39440061, 2024).
glioma (6 papers, 2010 to 2025). A benign or malignant brain and spinal cord tumor that arises from glial cells (astrocytes, oligodendrocytes, ependymal cells). "Another study later corroborated that high CCT6A levels in glioma correlate with elevated WHO grade, fewer IDH1/2 mutations and shorter overall survival." (PMID 38212481, 2024). "NEAT1 promoted glioma progression via miR-152-3p/CCT6A and miR-132/SOX2 pathway." (PMID 36523600, 2022). "In particular, EVs obtained from CUSA (cavitron ultrasonic surgical aspirator) samples during GBM surgeries showed higher levels of all eight CCT subunits compared with those from low-grade gliomas, with CCT1, CCT2, CCT6A, and CCT7 being the most prominently upregulated." (PMID 41516249, 2025). "Moreover, analyses of gene expression and DNA copy number showed that CCT2, CCT3, CCT5, CCT6A, and CCT7 are upregulated in GBM compared with normal brain tissue, while CCT2, CCT3, CCT5, CCT6A, and CCT8 display higher copy numbers than in low-grade gliomas." (PMID 41516249, 2025). "The expression of 5 genes (VSTM2A, SEPT14, MRPS17, PSPH and CCT6A) was undetectable in all these gliomas, regardless of their amplification status." (PMID 21170331, 2010). "Moreover, lncRNA NEAT1 promotes glioma pathogenesis though many of other pathways including NEAT1/miR-449b-5p/c-Met axis, NEAT1/MiR-92b, TLR9/NEAT1/STAT3, NEAT1/microRNA let-7e, miR-152-3p/CCT6A, and miR-139-5p/CDK6." (PMID 33393590, 2021).
lung adenocarcinoma (5 papers, 2022 to 2025). A carcinoma that arises from the lung and is characterized by the presence of malignant glandular epithelial cells. "To delve into CCT6A’s intrinsic mechanisms affecting glycolysis and proliferation in lung adenocarcinoma, we employed transcriptomic sequencing and liquid chromatography-mass spectrometry analysis." (PMID 38750462, 2024). "However, the amplifications, expressions, and the prognostic effects of CCT6A and CHCDH2 in lung adenocarcinoma (LUAD) are unclear." (PMID 35937942, 2022).
hepatocellular carcinoma (4 papers, 2020 to 2024). A malignant tumor that arises from hepatocytes. "For example, there is a significant difference in the expression of TCP1/CCT2/CCT3/CCT4/CCT5/CCT6A/CCT7/CCT8 in hepatocellular carcinoma." (PMID 37058032, 2023). "In hepatocellular carcinoma (HCC) cells, CCT6A knockdown downregulates cyclin D to suppress proliferation by decelerating the G1/S transition." (PMID 38363102, 2024). "As to CCT6A, a few recent data reveal that CCT6A promotes cell proliferation and metastasis in various cancers (such as NSCLC, colon carcinoma, and hepatocellular carcinoma (HCC))." (PMID 32631353, 2020). "GPR50, significantly upregulated in hepatocellular carcinoma (HCC) patients and the CBRH-7919 cell line, promotes HCC progression by enhancing cell proliferation, migration, and autophagy, mediated through interactions with CCT6A and PGK1, suggesting GPR50 as a potential therapeutic target for HCC." (PMID 39315094, 2024).
melanoma (4 papers, 2018 to 2022). A malignant, usually aggressive tumor composed of atypical, neoplastic melanocytes. "For instance, CCT6A is upregulated in drug-resistant variants of the human melanoma cell line compared with the parental human melanoma cell line." (PMID 32631353, 2020). "Recent studies indicate that CCT6A expression is significantly increased in ten human tumor cell lines and drug-resistant human melanoma cell lines." (PMID 36584147, 2022). "Previous research on cancer has found that CCT6A expression is upregulated in drug-resistant human melanoma cell lines." (PMID 36584147, 2022). "In the case of melanoma immunotherapy, mutated TCP 1-zeta-6A (CCT6A) antigen had previously been identified and proved to be immunogenic in a melanoma patient, so mutated CCT6A peptide was used as a model for patient-specific neoantigen." (PMID 29360750, 2018).
colon carcinoma (3 papers, 2020 to 2024). "Also, CCT6A knockdown dramatically decreases the proliferation of colon carcinoma cells." (PMID 32631353, 2020).
lymph node metastasis (3 papers, 2020 to 2024). "Moreover, tumor CCT6A high expression was associated with lymph node metastasis (P = 0.001), elevated TNM stage (P = 0.002), and abnormal carcinoembryonic antigen (P = 0.022)." (PMID 32631353, 2020). "Elevated CCT6A expression in TNBC patients was associated with an adverse prognosis and lymph node metastasis." (PMID 39556022, 2024). "Given that CCT6A is highly expressed in lymph node metastasis patients, we sought to determine whether CCT6A affects cell migration and invasion." (PMID 39556022, 2024).
non-small cell lung carcinoma (2 papers, 2020 to 2022). A group of at least three distinct histological types of lung cancer, including non-small cell squamous cell carcinoma, adenocarcinoma, and large cell carcinoma. "CCT6A has also been shown to suppress decapentaplegic homolog 2 (SMAD2) function in non-small cell lung cancer (NSCLC) cells and to promote metastasis by directly binding to SMAD2 protein, while the selective inhibition of CCT6A efficiently suppresses TGF-β-mediated metastasis." (PMID 36584147, 2022). "This study aimed to investigate the correlation of chaperonin containing t-complex polypeptide 1 subunit 6A (CCT6A) expression with clinicopathological features and survival profiles in non-small cell lung carcinoma (NSCLC) patients." (PMID 32631353, 2020).
pancreatic cancer (2 papers, 2023 to 2025). "Mouse pancreatic cancer cells (KPC cells) were stably transfected with either CCT6A-targeting shRNA or scramble shRNA." (PMID 40374617, 2025). "Additionally, comprehensive analysis of pathological staining revealed that anti-CD47 nanobody therapy more effectively reduced the infiltration of F4/80+CD163+ TAMs and increased the infiltration of F4/80+CD86+ TAMs in pancreatic cancer with CCT6A knockdown." (PMID 40374617, 2025). "The role of CCT protein in pancreatic cancer was not clear, while CCT6A was reported to promote TGF-β signal transduction in prostate cancer, which may promote fibrosis in pancreatic cancer." (PMID 38304253, 2023).
autoimmune disease (1 paper, 2024). A disorder resulting from loss of function or tissue destruction of an organ or multiple organs, arising from humoral or cellular immune responses of the individual to their own tissue constituents. "The levels of CCT6A, a subunit of the CCT complex, are increased in plasma from patients with autoimmune diseases such as systemic lupus erythematosus (SLE) and rheumatoid arthritis (RA), in which CCT6A may represent an autoantigen recognizable by γδ T cells." (PMID 38334609, 2024).
brain malformations (1 paper, 2025). "Recent reports provide evidence for presence of variants in several TRiC/CCT members including CCT1, CCT3, CCT5, CCT6A, CCT7 and CCT8, in brain malformations, seizures, and intellectual disability." (PMID 40779003, 2025).
cervical cancer (1 paper, 2022). A primary or metastatic malignant neoplasm involving the cervix. "Likewise, high expression of CCT6A confers an unfavorable outcome in various tumor entities such as breast or cervical cancer, and CCT6A is secreted in extracellular vesicles." (PMID 36291816, 2022).
COVID-19 (1 paper, 2025). A disease caused by infection with severe acute respiratory syndrome coronavirus 2. "Remarkably, telomere maintenance processes were observed to be one of the top biological processes activated in patients with mild COVID-19 via activation of genes such as CCT2, CCT3, CCT4, CCT5 and CCT6A." (PMID 41141600, 2025).
esophageal squamous cell carcinoma (1 paper, 2024). Esophageal squamous cell carcinoma (ESCC) is a type of esophageal carcinoma (EC) that can affect any part of the esophagus, but is usually located in the upper or middle third. "In esophageal squamous cell carcinoma (ESCC), Chaperone-containing TCP1 subunit 6A (CCT6A) stimulates the TGF-β/Smad/c-Myc pathway, thereby promoting ESCC EMT and cell invasiveness." (PMID 38818471, 2024).
fibrosis (1 paper, 2024). the formation of excess fibrous connective tissue in an organ or tissue in a reparative or reactive process. "Finally, we evaluated the efficacy of targeted Cct6a in mice with BLM-induced fibrosis." (PMID 38760881, 2024).
mucinous adenocarcinoma (1 paper, 2024). An invasive adenocarcinoma composed of malignant glandular cells which contain intracytoplasmic mucin. "Subsequently, we observed that expression of CCT6A was higher in both mucinous adenocarcinoma and adenocarcinoma than that in the normal tissues at both transcriptional level and protein level." (PMID 39440061, 2024).
osteosarcoma (1 paper, 2022). A usually aggressive malignant bone-forming mesenchymal neoplasm, predominantly affecting adolescents and young adults. "Transfection of CCT6A small interfering RNA into cultured osteosarcoma cells revealed that CCT6A knockdown attenuates cell growth, cell viability, cell survival, and induced apoptosis and cell cycle progression at the G0/G1 phases." (PMID 36584147, 2022). "Using data from the R2 online genomic analysis and visualization application, we found that CCT6A messenger ribonucleic acid (RNA) expression is increased in osteosarcoma tissue and cells." (PMID 36584147, 2022). "We assessed the role of the protein-coding gene chaperonin-containing TCP1 subunit 6A (CCT6A) in osteosarcoma, as this is currently unknown." (PMID 36584147, 2022). "Our study has some potential limitations, because we focused on the role of CCT6A in osteosarcoma cells without considering its effect on the tumor microenvironment and immune components." (PMID 36584147, 2022).